U3 (Small nucleolar RNA U3 )
Synonyms: LOC124906194
Gene: Small nucleolar RNA gene on chromosome 2 (114,005,440 to 114,005,655, reverse strand). Ensembl gene ENSG00000212182.
Gene Ontology:
Biological process: RNA processing
Cellular component: nucleolus
Homologues: Orthologues: chimpanzee U3 (99% identical), macaque U3 (90% identical). Paralogues in human: SNORD3P1 (81% identical), SNORD3G (80% identical), SNORD3E (79% identical), U3 (79% identical), SNORD3D (78% identical), U3 (78% identical), U3 (77% identical), U3 (75% identical), U3 (74% identical), SNORD3H (74% identical), U3 (73% identical), U3 (72% identical), and 13 more.